PPARA (peroxisome proliferator activated receptor alpha)
Diseases named in the same sentence as PPARA in open-access papers (continued):
Sharing a sentence is not in itself a finding about the gene and the disease.
dyslipidemia (continued). "High fructose promotes the methylation levels of PPARα and CPT1A in rat liver, suggesting that DNA methylation status of PPARα and CPT1A is closely associated with the pathogenesis of fructose-induced metabolic syndrome." (PMID 34362460, 2021). "PPARα agonist fibrates were introduced more than 35 years ago to improve the serum lipid profile and reverse atherogenic dyslipidemia." (PMID 34745420, 2021). "Fibrates are PPARα agonists used to treat problems such as dyslipidemia and hypercholesterolemia; however, there is various evidence that demonstrate its effectiveness in reducing alcohol consumption in mice and rats." (PMID 34361064, 2021). "8-HEPE activated the transcription of PPARs leading to increased adipogenesis and cellular glucose uptake in fibroblasts and muscle cell-lines, and improved dyslipidemia in a PPARα-dependent manner." (PMID 34604280, 2021). "Use of hepatocyte-specific PPARδ null mice identified that hepatic PPARβ/δ augments FA muscle utilization and improves dyslipidemia through a metabolic network between hepatic PPARβ/δ and muscle PPARα." (PMID 34361064, 2021). "Pharmacological targeting of PPARα activation has been demonstrated to be one of the important strategies for patients with diabetes, metabolic syndrome, and atherosclerotic cardiovascular diseases." (PMID 33397369, 2021). "The novelist finding of this study is the ability of both doses of the beetroot extract to attenuate the increase in the levels of SREBP1/2 and stimulate PPARα to attenuate dyslipidemia hepatic lipid synthesis in T2DM-induced rats." (PMID 34943221, 2021). "Fibrates have shown more selectivity and high potency as PPARα agonists, and they have been used in the treatment of atherogenic dyslipidemia and hypercholesterolemia." (PMID 33995008, 2021). "Many exogenous peroxisome proliferators (PP) are agonists of PPAR, as evidenced by the fact that PPARγ and PPARα are respective molecular targets for the type 2 diabetes drug thiazolidinediones (TZDs) and for dyslipidemia drug fibrates." (PMID 34681767, 2021). "Fenofibrate is clinically used to treat dyslipidemia via activation of PPARα, and also inhibited the cytopathic effect exerted by SARS-CoV-2 on Vero E6 at 20 μM." (PMID 33841165, 2021). "Quercetin-3-O-β-d-glucuronide (Q3GA) ameliorates dyslipidemia in fatty livers by modulating the PPARα/sterol regulatory element-binding protein-1c (SREBP-1c) signaling." (PMID 34445672, 2021). "Peroxisome proliferator-activated receptor alpha (PPARA) is the molecular target of fibrates commonly used to treat dyslipidemia and diabetes." (PMID 33959155, 2021). "Lecka-Czernik B reported that Aleglitazar, being developed by Roche Holding, is a dual agonist for PPARD and PPARA for the promising multiple treatment of hyperglycemia and dyslipidemia with T2DM patients." (PMID 33382706, 2020). "Further investigations utilizing human PPARα transgenic mice are needed to better exploit the utility of animal studies in exploring the role of PPARα in human-relevant metabolic syndrome and NAFLD models." (PMID 35296120, 2020). "Small-molecule agonism of peroxisome proliferator-activated receptor α (PPARα), a ligand-activated transcriptional factor involved in regulating fatty acid metabolism, is an important approach for treating dyslipidemia." (PMID 32376995, 2020). "The previous work on peroxisome proliferator-activated receptor α (PPARα) has indicated that PPARα can regulate lipid and glucose metabolism in the treatment of dyslipidemia and diabetes." (PMID 32655764, 2020). "Because of this property, a number of PPARα agonists are in clinical use for the treatment of hypertriglyceridemia and atherogenic dyslipidemia." (PMID 32588087, 2020). "Preclinical data indicate that pemafibrate has beneficial effects on atherogenic dyslipidemia, inflammation, and atherosclerosis by modulating PPARα-mediated gene expressions." (PMID 31974794, 2020).
dyslipidemia (continued). "Fibrates are PPARα agonists used for their capacity to lessen the dyslipidemia of MetS characterized by elevated TG and reduced HDL-cholesterol levels." (PMID 32630256, 2020). "In the fibrate class, fenofibric acid (fenofibrate) was developed as a PPARα agonist for the treatment of dyslipidemia." (PMID 31935812, 2020). "The selective PPARα modulator (SPPARMα) is expected to medicate dyslipidemia with minimizing adverse effects." (PMID 31935812, 2020). "A few studies have reported the efficiency of combined PPARα and PPARγ agonist therapy for diabetes and dyslipidemia." (PMID 32707656, 2020). "PPARα/γ dual agonists have been in clinical development for the treatment of metabolic diseases including type 2 diabetes and dyslipidemia." (PMID 31918918, 2020). "Pemafibrate is a novel selective PPARα modulator, which has been reported to improve atherogenic dyslipidemia, in particular, hypertriglyceridemia and low HDL-cholesterol." (PMID 32584895, 2020). "Fibrates are synthetic ligands of PPARα and are commonly used for treatment of metabolic disorders that display dyslipidemia, such as non‐alcoholic fatty liver disease (NAFLD), cardiovascular disease, and type 2 diabetes." (PMID 31916705, 2020). "Our study revealed the potential of using 1H-pyrazolo-[3,4-b]pyridine as a skeleton for developing potent PPARα agonists and provides clues for their structure-based optimization to develop novel drugs for dyslipidemia." (PMID 32376995, 2020). "Tesa is a dual agonist of PPARα and γ that improves both lipidemic and glycemic abnormalities in preclinical models of type 2 diabetes and metabolic syndrome." (PMID 31918918, 2020). "The implication of PPARs in lipid homeostasis and the greater risk for obesity and dyslipidemia in ASD compared to the general population, suggest a role for PPARα in metabolic dysregulation in patients with ASD." (PMID 30995737, 2019). "Since the lipid-lowering activity of PPARα agonists and insulin-sensitizing effect of PPARγ agonists are extremely well-established and have been widely exploited to improve dyslipidemia and T2DM, these aspects will be excluded from this review." (PMID 31614690, 2019). "The advantages of PPARα and PPARγ agonists in the treatment of metabolic syndrome have led to the development of PPARα/γ dual agonists." (PMID 30733541, 2019). "Fibrates (PPARα agonists) and TZDs (PPARγ agonists) remain two of the mainstream therapeutic agents for dyslipidemia, T2DM, and CVD prevention." (PMID 31614690, 2019). "Pemafibrate, due to its high selectivity, is likely to replace other PPARα agonists for dyslipidemia and cardiovascular diseases." (PMID 31614690, 2019). "PPARα is strongly expressed in tissues with a high mitochondrial and peroxisomal β‐oxidation activity, such as the heart, liver, kidney, and intestine, and activation of PPARα results in enhancement of fatty acid oxidation and improvement of dyslipidemia." (PMID 31367355, 2019). "The combined use of PPARα agonists and statins is a useful option for the treatment of atherogenic dyslipidemia." (PMID 31698825, 2019). "Given the superior efficacy and high selectivity, pemafibrate is expected to overtake conventional PPARα agonists, in particular, fenofibrate, as the primary fibrate-based lipid-lowering drug in the treatment of dyslipidemia and CVD." (PMID 31614690, 2019). "Lastly, the development of the selective PPARα agonist, i.e., pemafibrate, offers a new dawn in the approach to address the treatment gap related to atherogenic dyslipidemia." (PMID 31489930, 2019). "Typically, PPARα is activated by fibrates, which are commonly used therapeutic agents in the treatment of dyslipidemia." (PMID 30060458, 2018). "Drugs for treating dyslipidemia via activating PPARα, especially represented by fibrates, are also widely used." (PMID 30060458, 2018).
dyslipidemia (continued). "In summary, E. coli-induced acute lung infection aggravated dyslipidemia in mice by inhibiting PPARα related fatty acid oxidation pathway and activating SREBP-1c related lipid synthesis pathway, which resulted from the decreased phosphorylation of AMPKα." (PMID 30398974, 2018). "The partial agonist activity of idebenone on both PPARα and PPARγ, combined with its excellent safety profile in humans, suggested a potential role in the treatment of metabolic syndrome diseases." (PMID 30171034, 2018). "Fibrates, such as PPARα activators, have been used for decades in the management of combined dyslipidemia." (PMID 30060458, 2018). "Agonists of PPARα and PPARβ/δ have been used to treat dyslipidemia by increasing oxidative capacity in muscle fibers and improving insulin sensitivity." (PMID 30037087, 2018). "For example, PPARα activators such as fibrates (fenofibrate, clofibrate) are useful drugs for the treatment of dyslipidemia." (PMID 30060458, 2018). "PPARα is increasingly described as a potential molecular target of the hypolipidemic drugs for the treatment of dyslipidemia and fibrates." (PMID 29997323, 2018). "Pharmacological targets of PPARα and PPARγ are relatively well-known in the therapies of dyslipidemia and diabetes." (PMID 29358945, 2017). "Fibrates, including fenofibrate and clofibrate, are well-known pharmacological PPARα agonists widely used to treat dyslipidemia." (PMID 28139735, 2017). "Similar to previous studies, we observed that a HFD resulted in lipid metabolic disorder, and GTP treatment alleviated dyslipidemia and reduced fat deposited in the liver by increasing the mRNA and protein expressions of hepatic PPARα in HFD-fed animals." (PMID 28777810, 2017). "Dual agonists are a class of drugs that activate both PPARα and PPARγ, thereby combating diabetes mellitus and the metabolic syndrome among patients diagnosed with both conditions." (PMID 28348577, 2017). "Thus, it provides evidence that PPARα/γ may influence the risk of dyslipidemia and CVD via Lp (a)." (PMID 29358945, 2017). "Recently, a highly potent and selective PPARα agonist (K-877) has shown positive effects on atherogenic dyslipidemia." (PMID 27347932, 2016). "The dual PPARα/δ agonist (GFT-505) has shown favorable results in improving atherogenic dyslipidemia and insulin resistance and appears to be a potential candidate for the treatment of non-alcoholic fatty liver disease (NAFLD)." (PMID 27347932, 2016). "More specifically, PPARα regulates lipid metabolism by targeting fatty acid and acyl-CoA and thus acts as protective factor in dyslipidemia, whereas PPARγ increases tissue insulin sensitivity and is a pharmaceutical target in diabetes mellitus." (PMID 27022389, 2016). "Fenofibrate, a PPARα agonist, and pioglitazone, a PPARγ agonist, are widely used in the clinical setting for the management of dyslipidemia and insulin resistance." (PMID 26770990, 2016). "PPARα agonists have been proposed as a breakthrough in the management of dyslipidemia to reduce blood triglyceride levels." (PMID 27242912, 2016). "Particularly, fibrates, well-known PPARα agonists, are commonly prescribed for the treatment of dyslipidemia." (PMID 27559343, 2016). "In particular, dual PPARα and PPARγ agonists have been accepted to be promising for the treatment of type 2 diabetes with dyslipidemia." (PMID 28042289, 2016). "In fact, zerumbone has been shown to ameliorate dyslipidemia in high-fat diet-induced hyperlipidemic hamsters through the enhancement of gene expression involved in the lipid metabolism through PPARα activation." (PMID 27973425, 2016). "PPARA is activated by long chain unsaturated fatty acids, eicosanoids, and synthetic fibrates, which have been developed to treat dyslipidemia by reducing triglyceride levels." (PMID 26697060, 2015).
dyslipidemia (continued). "The insulin sensitizing effects of the PPARγ agonists combined with the lipid-lowering effects of the PPARα agonists would theoretically be efficacious in treating patients with metabolic syndrome or type II diabetes." (PMID 26713088, 2015). "Fibrates, such as fenofibrate, bezafibrate, ciprofibrate, and clofibrate, are PPARα agonists used clinically for treating dyslipidemias such as primary hypertriglyceridemia, combined hyperlipidemia, and primary hypercholesterolemia." (PMID 26713088, 2015). "Our study demonstrated that consumption of AE improved dyslipidemia by through promoting the expression of the lipolytic genes PPARα, ACC2 and CPT1 and inhibiting the expression of lipogenic genes like SREBP-1c, FAS, and ACC1." (PMID 26438035, 2015). "To date, the nuclear receptor PPARβ/δ has been less studied than PPARα and PPARγ, which are drug targets for the treatment of dyslipidemia and type 2 diabetes, respectively." (PMID 24203162, 2014). "Fenofibrates, PPARα agonists, have been investigated in-depth for their beneficial effects on various features of the metabolic syndrome." (PMID 25500563, 2014). "Given the complex regulation of PPARα activation and its importance in the control of dyslipidemia, this justifies the identification of novel regulators and effectors of its function." (PMID 25141153, 2014). "Some synthetic PPAR ligands have been widely used in the treatment of dyslipidemia (e.g., fibrates–PPARα activators) and diabetes mellitus (e.g., thiazolidinediones–PPARγ agonists)." (PMID 25158235, 2014). "Synthetic ligands are widely used in the treatment of dyslipidemia (e.g. fibrates - PPARα activators) or in diabetes mellitus (e.g. thiazolidinediones - PPARγ agonists)." (PMID 24524207, 2014). "Our aim was therefore to assess the distribution of the APOE, SCARB1, PPARα genotypes in the Lithuanian adult population and to determine the relationship of these genotypes with dyslipidemia." (PMID 23919842, 2013). "Peroxisome proliferator-activated receptor (PPAR) γ agonists, thiazolidinediones, are used for the treatment of type 2 diabetes, and PPARα agonists belonging to the fibrate class of compounds are used for the treatment of dyslipidemias." (PMID 24285952, 2013). "PPARγ agonists thiazolidinediones (TZDs) and PPARα agonist fibrates are widely used as pharmacological agents in the treatment of diabetes and dyslipidemia, respectively." (PMID 23594962, 2013). "For example, fibrates, the PPARα agonist, have been in clinical use for the treatment of dyslipidemia." (PMID 24147098, 2013). "Mice transgenic for human TNFα (hTNFα) have previously been shown to display dyslipidemia, altered lipid composition, and reduced activation of peroxisome proliferator-activated receptor alpha (PPARα) regulated genes." (PMID 24098955, 2013). "The objective of this study was to assess the distribution of the APOE, SCARB1, PPARα genotypes in the Lithuanian adult population and to determine the relationship of these genotypes with dyslipidemia." (PMID 23919842, 2013). "Recently, it was reported that fenofibrate requires the PPARα gene to improve dyslipidemia and liver steatosis in mice after they were fed a western diet." (PMID 23704907, 2013). "Although PPARα agonists are used in clinic to treat mixed dyslipidemia and hypertriglyceridemia, few studies have investigated the outcomes of these treatments for NAFLD." (PMID 23024649, 2012). "A recent meta-analysis of trials involving hypertriglyceridemic patients demonstrated that fibrates reduce vascular events, suggesting a renewed interest in the activation of PPARα to prevent CVD in select patients with dyslipidemia." (PMID 22701469, 2012). "Today, PPAR agonists have clinical importance in management of dyslipidemia (such as clofibrate, a PPARα agonist) and reducing insulin resistance and antidiabetic activity (such as rosiglitazone, a PPARγ agonist)." (PMID 22701496, 2012).
dyslipidemia (continued). "PPARα is employed as a successful target for pharmaceutical intervention in humans with fibrate drugs being important in treatment of dyslipidemia and cardiovascular disease." (PMID 22550474, 2012). "These authors demonstrated a significant increase in hepatic PPARα protein expression, suggesting that an increase in fatty acid oxidation leads to the observed attenuation of hepatic steatosis and improved dyslipidemia." (PMID 22701469, 2012). "The PPARs have already yielded viable targets for the treatment of T2DM and dyslipidemia; thiazolidinediones, PPARγ agonists, are currently used in the clinic for the treatment of T2DM; and fibrates, PPARα agonists, are routinely used to treat dyslipidemia." (PMID 21843327, 2011). "Several glitazones (PPARγ agonists) and glitazars (dual PPARα/γ agonists) have been developed to treat hyperglycemia and, simultaneously, hyperglycemia and dyslipidemia, respectively." (PMID 21533120, 2011). "Synthetic drugs activating PPARα and PPARγ are in clinical use: the former typified by fibrates, are used to treat dyslipidemia, while the latter include glitazones that act as insulin sensitizers in type 2 diabetes mellitus." (PMID 21533120, 2011). "The first evidence of the in-vivo anti-inflammatory action of PPARα agonists in humans came from the studies performed on patients with hyperlipidemia and metabolic syndrome." (PMID 21760804, 2011). "PPARα agonists, such as fibrates, have been used for many years for treating dyslipidemia, mainly due to their actions of lowering TG levels." (PMID 20211032, 2010). "Long before beingidentified as PPARα agonists,fibrates were clinically prescribed for treatment of dyslipidemia.Subsequently, TZDs, structural analogues of fibrates, were shown to selectivelyactivate PPARγ." (PMID 18401459, 2008). "The seminal evidence that placed PPARα at the center of lipoprotein metabolismwas the demonstration that fibrates, which had been used clinically for many years to treat dyslipidemia, act by binding to PPARα andinduce PPARα-dependent gene transcription." (PMID 18288277, 2008). "Activation of PPARα by its natural or synthetic ligands enhances FA uptake and oxidation in liver, which is beneficial for ameliorating dyslipidemia." (PMID 18401459, 2008). "PPARA (NR1C1, Gene ID: 5465) is located on 22q13.3, and several single nucleotide polymorphisms described within this gene were associated with metabolic features like insulin resistance, dyslipidemia and cardiovascular risk factors." (PMID 40806580, 2025). "Pan-NR agonists, such as RGX-202, activate PPARα, PPARγ, and PPARδ, leading to improvements in lipid metabolism, insulin sensitivity, and fatty acid oxidation, with potential applications for metabolic syndrome, dyslipidemia, and CVD." (PMID 40926269, 2025). "This is consistent with the fact that FF improves dyslipidemia by mediating PPARα." (PMID 39857794, 2025). "Beginning one week after tumor inoculation and continuing for a total of 7 days, the mice received a daily intraperitoneal (i.p.)injection of either DMSO (control) or pemafibrate (Pem), a highly selective PPARα agonist used in humans for the treatment of metabolic syndrome." (PMID 39910334, 2025). "Fenofibrate is a synthetic PPARα agonist used in the treatment of dyslipidemia and may also exert antidepressant-like effects." (PMID 40943672, 2025). "In addition, PPAR agonists (such as fibrates for PPARα and glitazone for PPARγ) have been used for decades to treat dyslipidemia and diabetes." (PMID 38925330, 2024). "Notably, PPARα agonists are known for their significant role in the treatment of dyslipidemia or metabolic syndromes by reducing plasma triglyceride levels together with the modulation of glucose homeostasis and insulin resistance." (PMID 38611871, 2024). "Moreover, PPARA has been shown to undergo hydroxymethylation modifications that influence its expression, predisposing individuals to NAFLD and the development of metabolic syndrome." (PMID 39595621, 2024).